CASP8 (caspase 8)
Diseases named in the same sentence as CASP8 in open-access papers (continued):
Sharing a sentence is not in itself a finding about the gene and the disease.
cervical carcinoma (continued). "In cervical cancer, however, type I interferons induced apoptosis via the extrinsic pathway by balancing cFLIP and caspase-8 independent of death ligands." (PMID 29581840, 2018). "Notably, our research underscored that combining a small-molecule CDK9 inhibitor with Cisplatin elicited a synergistic inhibition of the cervical cancer cell growth under both 2D and 3D culture conditions, particularly in cases lacking Caspase-8 expression." (PMID 38201534, 2023). "In light of these findings, we could show that the knock-down of TGM2 expression dramatically decreased the ability of cervical cancer cells lacking Caspase-8 expression to migrate." (PMID 36399280, 2022). "However, the most intriguing aspect of our study is finding a previously unknown non-apoptotic function of Caspase-8 in cervical cancer as a negative regulator of CDK9 kinase activity in vitro." (PMID 36399280, 2022). "Therefore, understanding the non-apoptotic functions of Caspase-8 could help overcome cervical cancer metastasis and chemoresistance." (PMID 36399280, 2022). "However, the effect of quercetin on CASP8 in cervical cancer has not been reported." (PMID 35070983, 2021). "To determine whether myricetin and spinacine re-sensitize SiHa cells to TRAIL-induced apoptosis by specifically blocking the binding of E6 to caspase 8, we compared responses in the HPV+ SiHa cells with those from the HPV− human cervical carcinoma cell, C33A, as these cells do not express E6." (PMID 26794656, 2016).
viral infection (41 papers, 2011 to 2026). "Lastly, viral infection elicits the production of TNF that can act in an autocrine/paracrine manner to initiate apoptosis in the presence of functional caspase-8, or necroptosis via the association of RIPK1 with RIPK3 in its absence." (PMID 35549723, 2022). "In agreement, the specific deletion of caspase-8 in the T cell lineage leads to immunodeficiency associated with impaired T cell homeostasis, T cell lymphopenia, defective T cells proliferation after stimulation with mitogens or antigens, and impaired responses to viral infection." (PMID 24587805, 2014). "Inhibition of caspase-8 activation during viral infections triggers necroptosis as a secondary antiviral cell death response pathway." (PMID 41190811, 2025). "PRV VP22 disrupts the binding between ZBP1 and RIPK3/Caspase-8 and inhibits the cleavage of Caspase-1 and IL-1β induction, thereby promoting viral infection." (PMID 39475237, 2024). "Apoptosis induction by viral infection has been shown to be dependent on Puma for apoptosis via Bax/Bak activation; viral infection leads to caspase-8 activation and, hence, Bid cleavage and activation." (PMID 36298777, 2022). "Intriguingly, patients with early-onset IBD caused by a deficiency in caspase-8, a scaffold required for synergistic activation of JAK1/2-STAT1 and IEC death as identified herein, were also increasingly susceptible to viral infections." (PMID 34556638, 2021). "When expressed independently of virus infection, vICA binds to the pro-domain of CASP8 and prevents TNF-, Fas-, or RIPK3 inhibitor-dependent apoptosis in fibroblasts." (PMID 33126536, 2020). "dsRNA produced during the course of virus infection can be a potent inducer of cell death, through pathways that can involve both caspase-8 and -9." (PMID 31083335, 2019). "We found that HuN4 viral infection induced the cleavage of caspase-3 and caspase-8 from 7 dpi, which persisted at 10 dpi." (PMID 26046751, 2015). "TNF receptor signaling, viral infection, Caspase-8 inhibition." (PMID 40831559, 2025). "Therefore, we examined the interactions between RIPK3 and ZBP1 or Caspase-8 during viral infections." (PMID 39475237, 2024). "In NLRP1 deficient cells, virus infection fails to induce caspase-8/-3 activation and subsequent GSDME cleavage." (PMID 38932190, 2024). "Casp8−/− natural killer cells have defects in accumulating in response to viral infection." (PMID 38637559, 2024). "Studies have shown that viral infection could induce apoptosis in cultured PK-15 cells by requiring the activation of caspase-8 and effector caspase-3 pathways." (PMID 34211446, 2021). "Thus, these discoveries have expanded the role of caspase-8 in the regulation of inflammatory responses to the context of virus infection." (PMID 33037188, 2020). "RIG-I recruits RIP-1 and caspase-8 complex after viral infection." (PMID 25754842, 2015). "Little difference in the amount of the caspase-8 precursor that was present was shown even 96 hours post virus treatment compared with before viral infection, indicating that the apoptosis induced by Ad.SPDD-HCCS1 may occur via the mitochondrial pathway." (PMID 22040050, 2011). "Although blocking apoptosis through restricting caspase-8 in IEC and switching their death to necroptosis cause overt intestinal inflammation, it may be a self-protection mechanism evolved by the body when the caspase-8-dependent apoptotic pathway has been hijacked by microbes or viral infection." (PMID 39840043, 2024). "However, in Casp8−/−Ripk3−/− mice, double-deficient MCMV exhibited a spread in viral titer, indicating TNF-CASP8-dependent signaling may amplify the innate immune response to restrict virus infection in vivo." (PMID 34578288, 2021). "Vero E6 cells were pretreated with Z-IETD-FMK (caspase-8 inhibitor) or Z-LEHD-FMK (caspase-9 inhibitor) at concentrations of 50 and 100 μM or DMSO, followed by viral infection." (PMID 32090691, 2020).
viral infection (continued). "Such synchronous gene expression for CASP2L, CASP8 and IAP suggested that virus-induced apoptotic response was critically modulated during viral infection of insect vectors." (PMID 30653614, 2019). "Viral infections have been reported to simultaneously trigger necroptosis and RIPK3/caspase-8 mediated apoptosis within mammalian fibroblasts and lung epithelial cells." (PMID 29643440, 2018). "For example, G2/I2 showed hyper-editing of type 1 interferon (IFN) receptors (IFNAR1 and IFNAR2), type 1 IFN-stimulated genes (ISGs) (e.g., EIF2AK2, DDX58/RIG-1, MAVS, TRIM56, and TRIM69) and genes involved in immune responses to viral infection (EIF2AK2, DDX58/RIG-1, MAVS, CASP8, CYCS, and HMGB1)." (PMID 35406793, 2022). "In this study, CASP8, IL22 and TLR3 were chosen to be used as target genes to assess the performance of the shortlisted reference genes, because these three genes play important roles in the innate immune response against virus infection." (PMID 32444639, 2020). "We also showed that exogenous TRAIL can directly increase the expressions of DR4/DR5 and then further enhance their downstream caspase-8-dependent apoptotic pathway in HTNV-infected HUVECs, which is a conventional mode of action present in various virus infection, such as reovirus or RSV." (PMID 32636833, 2020). "Here we show that overexpression of PKR in absence of a virus infection results in phosphorylation of eIF2α and induction of apoptosis that also involves activation of caspase-8 and -9." (PMID 30261686, 2018). "However, unlike in viral infection, deletion of ZBP1 in our fungal model did not result in a complete loss of CASP1 activation, GSDMD cleavage, or apoptotic protein (CASP8, CASP3, and CASP7) activation." (PMID 33109609, 2020). "CASP8 regulates both canonical and noncanonical NLRP3 inflammasome activation in bacterial and viral infections, and it also negatively regulates the necroptotic pathway." (PMID 33109609, 2020). "In addition to its role in inducing cell death, Caspase-8 also has a noncytotoxic role in modulating NK and CD8+ T cell responses to viral infection." (PMID 38578283, 2024). "On this basis, we were interested in studying the mediation of PKR in apoptosis in the absence of a virus infection and we used an approach of PKR overexpression, monitored phosphorylation of eIF2α and also included an assessment of involvement of caspase-8 and -9 in the process." (PMID 30261686, 2018).
pancreatic cancer (36 papers, 2003 to 2026). "Taken together, our results suggest that loss of the LUBAC subunit Rnf31 sensitizes murine and human pancreatic cancer to CTL killing by rendering cells susceptible to caspase-8-mediated apoptosis upon TNF signaling." (PMID 35379808, 2022). "Furthermore, TMX markedly enhanced the efficacy of TRA-8 therapy on tumorigenesis of the resistant PANC-1 pancreatic cancer cells in vivo, which was associated with increased expression of DR-5 and increased activation of the caspase-8." (PMID 26320171, 2015). "δ-T3 inhibits the proliferation of human pancreatic cancer cells and induces apoptosis through the activation of caspase-8 and caspase-3, both in vitro and in vivo." (PMID 39125998, 2024). "Further, in our quest to identify the executor pathway for pancreatic cancer cell death, we found Caspase 8 to be significantly increased in cells expressing TLR2- and TRL9-specific intrabodies compared to the control cells." (PMID 38390872, 2024). "Next, we tested the sensitivity of Jurkat and pancreatic cancer cells to TRAIL using a caspase-8 activation assay." (PMID 36775838, 2023). "In a recent study, Chen showed that pancreatic cancer cells cocultured with DNTs highly expressed Fas, caspase-8 and cleaved caspase-8, which are necessary in the Fas/FasL signalling pathway." (PMID 35287737, 2022). "The effects of VEDT were shown by its ability to trigger caspase-8-dependent apoptosis in pancreatic cancer cells." (PMID 31367187, 2019). "In the current study, we found that VEDT alone triggered a caspase-8-dependent apoptosis in pancreatic cancer cells; however, when combined with TRAIL, VEDT significantly augmented and potentiated the TRAIL-induced apoptosis of pancreatic cancer cells." (PMID 31367187, 2019). "A possible molecular target for VEDT is c-FLIPs, an inhibitor of caspase-8 in pancreatic cancer cells." (PMID 31367187, 2019). "Low-dose JNK plus TRAIL in pancreatic cancer cell lines revealed a significant increase in apoptosis compared to control by extrinsic caspase-8 activity (6E and Supplementary S3D)." (PMID 26840266, 2016). "Fifth, overexpression studies in pancreatic cancer cells indicated that both caspase-8 (CrmA) and NF-κB-dependent mitochondrial proteins (Bcl-2, and Mcl-1) were involved in the process of TRAIL sensitization." (PMID 22829912, 2012). "Pancreatic carcinoma cells are regarded as type II cells in which only small amounts of active caspase-8 are generated at the DISC and a mitochondrial amplification loop is necessary for proper apoptosis induction." (PMID 14583775, 2003). "Collectively, our study shows that targeting the caspase-8/c-FLIPL heterodimer in combination with the other drugs in pancreatic cancer cells is a promising direction that may provide a basis for further therapeutic strategies." (PMID 39753884, 2025). "In addition, the level of caspase 8, which is encoded by CASP8, was reduced in pancreatic cancer according to a previous study." (PMID 37234870, 2023). "In tumor cells, CASP8 induces apoptosis and inhibits proliferation and metformin was found to increase CASP8 expression in A498 renal carcinoma cells at 7.5 mmol/L after 24 h as well as in several pancreatic cancer cell lines at 30.0 mmol/L in vitro." (PMID 37313172, 2023). "Although, canonically, the activation of the extrinsic pathway (via caspase 8) triggers the induction of the intrinsic pathway, therefore caspase 9 activation, in pancreatic cancer cells, the activation of caspase 9 by HCA seems to be unrelated to the cell death induction." (PMID 36077299, 2022). "The effect of RPL39 on pancreatic cancer cell apoptosis seems to be dependent on caspase 8 activation suggesting that targeting RPL39 could be a potential treatment in pancreatic cancer." (PMID 34873618, 2021).
pancreatic cancer (continued). "Evidence suggests that CTD exerts cytotoxic effects on pancreatic cancer cells by JNK-dependent pathway, as CTD treatment suppressed pancreatic cancer cell proliferation via stimulating caspase-8 and caspase-9, upregulating expression level of Bad, Bid and Bak, while downregulating Bcl-2." (PMID 32707651, 2020). "Furthermore, VEDT was found to inhibit c-FLIPs expression and induce caspase-8-dependent apoptosis in pancreatic cancer cells, followed by caspase-3 and PARP1 cleavage in a time-dependent manner." (PMID 31367187, 2019). "In order to test this hypothesis, we tested caspase-8 activity induction by DR5Nb1-tetra in 27 pancreatic cancer cell lines with differential DR5 expression." (PMID 26378449, 2015). "Moreover, cleaved caspase 8 and 3 were seen at 48 h, whereas intrinsic apoptosis markers such as caspase 9 and Bax remained unaffected, in all rfhSP-D-treated pancreatic cancer cell lines as compared to untreated cells, which further confirmed the cell death via Fas-mediated pathway alone." (PMID 29915574, 2018). "To determine the specificity of nimesulide in the enhancement of TRAIL-induced apoptosis, we downregulated DR5 expression in pancreatic cancer cells using DR5 siRNA and tested caspase-8 activity in these cells." (PMID 36775838, 2023). "The apoptosis-induced cell death triggered by HCA was reversed by inhibiting caspase 8 activity, indicating that HCA mainly triggers death in pancreatic cancer cells through the extrinsic apoptotic pathway." (PMID 36077299, 2022). "We observed increased expressions of Bax, cleaved Caspase 3, cleaved Caspase 8 and cleaved PARP and while Bcl-2 expression was decreased in gedunin treated pancreatic cancer cells." (PMID 26988754, 2017). "Indeed, our results demonstrated an increase in activation of caspase-8 and caspase-9, followed by the cleavage of caspase-3 and PARP after the treatment of human pancreatic cancer cells with CSE." (PMID 33922003, 2021). "The pancreatic cancer cell line PaTu 8988t (column 2) showed strong expression of each of the proteins investigated, whereas the cell lines SW 480 and Panc-1 showed only expression of BAX, caspase-8, and caspase-9." (PMID 30686270, 2019). "In this study, we found that infection of VV-ING4 reduced the ratio of Bcl-2/Bax and induced the activation of Caspase 8/9/3 and PARP in SW1990 human pancreatic cancer cells, suggesting that Caspase-dependent apoptosis and the Bcl-2 family is participated in VV-ING4-induced cytotoxicity." (PMID 29137298, 2017). "Additionally, we have recently reported that TRA-8-induced DISC recruitment of PARP-1 regulates caspase-8 activation in the DISC, which is accompanied by enhanced sensitivity of pancreatic cancer cell to TRA-8-induced apoptosis." (PMID 26320171, 2015). "In contrast to brain tumour cells the expression of caspases is not limiting for apoptosis of pancreatic tumour cells and does not correlate with the sensitivity status of the cells under study expect for most sensitive Capan 1 cells, which expressed elevated levels of caspase-8, -9, and -7." (PMID 14583775, 2003). "Despite the intact expression of DR5, pancreatic cancer cells are not capable of initiating DR5 clustering and caspase-8 activity in the presence of ligand alone." (PMID 36775838, 2023). "In the pancreatic cancer cell line Panc-1, BAX expression was not influenced by incubation with staurosporine (column 1), whereas the signal strength of caspase-8 steadily increased in a time-dependent manner (column 2)." (PMID 30686270, 2019).
Sepsis (36 papers, 2008 to 2026). Sepsis is defined as life-threatening organ dysfunction caused by a dysregulated host response to infection. "We previously showed that GG treatment attenuates lymphopenia and restore the loss of CD4+ and CD8+ T cells in sepsis by inhibiting the expression of cleaved caspase-3 and caspase-8." (PMID 32677895, 2020). "Aberrant expression of caspase-8 is closely associated with the development and progression of a range of inflammatory diseases, including immune system disorders, neurodegenerative diseases (NDDs), sepsis, and cancer." (PMID 39379817, 2024). "Here, we identify Nemo-like kinase (NLK) as a novel regulator of Caspase-8-mediated PANoptotic signalling in sepsis." (PMID 41674095, 2026). "Collectively, these findings identify NLK as a regulatory rheostat of Caspase-8-associated PANoptosis in sepsis and highlight the NLK-Caspase-8 axis as a potential therapeutic target for fine-tuning sepsis-associated inflammatory cell death." (PMID 41674095, 2026). "Caspase-8 levels were significantly reduced in the sepsis group compared to healthy controls and cardiac patients in both adults and children." (PMID 40722817, 2025). "Equally significant is the consistent suppression of caspase-8 in both adult and pediatric sepsis cohorts when compared to healthy controls." (PMID 40722817, 2025). "Although CASP-8 has been extensively studied in conditions involving apoptosis and inflammatory responses, such as sepsis and autoimmune diseases, its role in serum sickness has not been well documented." (PMID 40557145, 2025). "Comparative analysis across diagnostic categories revealed that patients with sepsis exhibited significantly elevated levels of RIPK-1, IL-1β, and IL-18, along with reduced caspase-8 levels, relative to patients with SIRS or cardiac conditions." (PMID 40722817, 2025). "ROC analysis demonstrated strong predictive performance for sepsis/septic shock using RIPK1 (AUC = 0.81), IL-18 (AUC = 0.71), and A20 (AUC = 0.71); conversely, caspase-8 was inversely associated with sepsis (AUC = 0.32)." (PMID 40722817, 2025). "Pediatric patients demonstrated higher caspase-8 levels overall; however, within the sepsis group, caspase-8 was suppressed compared to healthy controls in both adults and children." (PMID 40722817, 2025). "Higher caspase-8 levels in blood or serum have been correlated to worse outcome for patients with spontaneous intracerebral hemorrhage and sepsis." (PMID 36945037, 2023). "During sepsis, casp-8 can be activated by signaling complex via death receptors, like FAS ligand or TNF-α." (PMID 35190789, 2022). "Our data showed a definitive correlation between upregulation of Fas and Fas-L expression and activation of caspase-8 in the spleen in sepsis." (PMID 30052667, 2018). "For instance, inhibition of apoptotic mediator such as caspase-8 increases mice resistance in sepsis model." (PMID 29209091, 2017). "The apoptosis during immune paralysis in sepsis is believed to be induced by caspase signals, namely death receptor induced caspase 8 (CASP8) or mitochondrial induced caspase 9 (CASP9)." (PMID 28056766, 2017). "Various pathways seem to be involved in the lymphocyte apoptosis in case of sepsis: an extrinsic pathway, mediated by the caspase-8, and an intrinsic pathway, mediated by the caspase-9." (PMID 28303547, 2017). "Here, we demonstrate that IL-1β production during sepsis with uropathogenic E. coli is mediated by caspase-8, since caspase-8 and RIPK3 double knock out mice show substantially lower cytokine during sepsis and increased survival after injection of TNFα." (PMID 28428949, 2017). "The death receptor Fas is upregulated on leucocytes in sepsis patients and caspase-8 is active in severe sepsis in animals." (PMID 18925930, 2008). "Interventional trials using RIPK1 inhibitors or caspase-8 modulators could test the therapeutic potential of modulating cell death pathways in sepsis." (PMID 40722817, 2025).